C1GALT1 (core 1 synthase, glycoprotein-N-acetylgalactosamine 3-beta-galactosyltransferase 1)
Diseases named in the same sentence as C1GALT1 in open-access papers (continued):
Sharing a sentence is not in itself a finding about the gene and the disease.
cancer (continued). "Overexpression of C1GalT1 expression in cancer cells disrupts the balance of competition among these glycosyltransferases and favors the formation of Core-1-associated carbohydrate structures, such as Galβ1,3GalNAcα-Ser/Thr." (PMID 34944925, 2021). "Studies have shown that C1GALT1 is abnormally expressed in a variety of malignant tumors, such as gastric cancer, head and neck cancer, pancreatic ductal adenocarcinoma, laryngeal carcinoma, ovarian cancer, and hepatocellular carcinoma." (PMID 34307388, 2021). "Overexpression of C1GALT1 has been observed in various cancer types, including breast, colorectal, stomach, head and neck, liver, ovarian and prostate cancers." (PMID 33420364, 2021). "As overexpression of SP1 occurs in many cancers, it is likely that SP1 overexpression makes an important contribution to the increased C1GalT1 expression in cancer." (PMID 34944925, 2021). "This review summarizes our current understanding of the expression of C1GalT1 in various cancers and discusses the impact of C1GalT change on cancer cell activities in cancer development and progression." (PMID 34944925, 2021). "Glycosylation of mucin proteins is therefore particularly prone to C1GalT1 expression changes in cancer." (PMID 34944925, 2021). "Change of mucin protein glycosylation in response to C1GalT1 alteration in cancer cells can lead to a significant change of the mucin protein communication with adjacent molecules and influence the activity and function of these molecules." (PMID 34944925, 2021). "Because the targeting of immune checkpoints seems promising in the treatment of several cancers, the regulatory role of C1GALT1 in immune responses warrants further investigation." (PMID 32005975, 2020). "Univariate analysis indicated that high C1GALT1 expression, advanced cancer stage, higher histological grade, and nodal metastasis significantly correlated with mortality." (PMID 32005975, 2020). "Our results suggest that, although other pathways exist, the anti-cancer effect of itraconazole in HNSCC is mainly through C1GALT1 inhibition." (PMID 29930379, 2018). "Identifying other acceptor substrates of C1GALT1 by glycoproteomics will be of great help to unravel the detailed mechanisms by which C1GALT1 regulates cancer behaviors." (PMID 24758762, 2014). "Similarly, MCM proteins, which are essential for DNA replication licensing and serve as emerging proliferation markers, were significantly associated with C1GALT1 expression—most notably MCM4 and MCM6, which were consistently correlated across cancers." (PMID 40548474, 2025). "These cancers also displayed lower C1GALT1 expression in tumors, supporting the hypothesis that hypermethylation may suppress gene expression." (PMID 40548474, 2025). "C1GalT1 median gene expression levels between different cancer types." (PMID 40548474, 2025). "Cancer types with significant differences in the C1GalT1 gene expression were examined to determine whether changes in DNA methylation could explain these variations." (PMID 40548474, 2025). "Furthermore, C1GALT1 knockdown also suppressed the proliferation of HuO3N1 and SaOS2 cell lines, both of which also reliably express C1GALT1 according to the Cancer Cell Line Encyclopedia." (PMID 38622340, 2024). "Further experiments demonstrated that C1GALT1 was absent in Cosmc-deficient cancer cells, consistent with previous reports indicating that the presence of T-synthase relies on intact Cosmc." (PMID 38699634, 2024). "The dysregulation of glycosyltransferases like C1GALT1, molecular chaperones like Cosmc, or the cellular environment can lead to the abnormal regulation of O-glycans, contributing to the development and progression of various cancers." (PMID 38699634, 2024).
cancer (continued). "C1GALT1 affects the behavior of cancer cells by altering the O-glycosylation on FGFR2, which promotes cancer cell invasiveness and stem cell-like properties.C1GALT1 also affects the epithelial-mesenchymal transition (EMT) of cancer cells, indicating its important role in cancer progression." (PMID 38699634, 2024). "In addition, overexpression of C1GALT1 reduces the radiosensitivity of A549 and H1299 cells to radiation, while inhibition of C1GALT1 expression can reverse the radioresistance of these cancer cells." (PMID 38662050, 2024). "These insights provide a comprehensive view of how C1GALT1 may influence cancer behavior and radioresistance." (PMID 38662050, 2024). "Furthermore, the current data indicated that C1GALT1 promotes EMT phenotype in A549 and H1299 cells, while inhibition of C1GALT1 abrogates EMT phenotype of cancer cells." (PMID 38662050, 2024). "This indicates that although the initial GalNAc residue in O-glycosylation biosynthesis is competed for by three types of glycosyltransferases (C1GalT1, β3GnT, and ST6GalNAc-transferase), C1GalT1 is probably the predominate force, at least in these cancer cells." (PMID 37612278, 2023). "This supports a positive role of C1GalT1 overexpression in promotion of cancer progression." (PMID 37612278, 2023). "Indeed, many cell membrane glycoproteins, for example integrins and MUC1 which are known to be involved in cancer progression, showed glycosylation changes in response to C1GalT1 suppression in this study." (PMID 37612278, 2023). "C1GALT1 overexpression has been reported for various cancers." (PMID 35864552, 2022). "Overexpression of C1GALT1 promotes the malignant properties of these cancer cells." (PMID 33420364, 2021). "To get an overall profile of C1GALT1 expression in different cancers, we analyzed the expression levels of C1GALT1 mRNA in 33 types of cancers using RNA-sequencing data derived from the Cancer Genome Atlas (TCGA) and Genotype-Tissue Expression (GTEx) databases." (PMID 34452648, 2021). "Targeting the activity of C1GalT1 or its regulators may have therapeutic potential in the development of novel cancer treatment strategies." (PMID 34944925, 2021). "In addition to integrin β1, which has repeatedly been demonstrated to be O-glycosylated and regulated by C1GALT1 in several cancers, we found that the α subunits of integrins, including αv and α5, were also modified by C1GALT1." (PMID 33420364, 2021). "Thus, we postulate that stimulatory effect of afzelin on GalNAcTL5 protein expression and inhibition of C1GalT1 in comparison to untreated control can be understood as potential anti-cancer action of the flavonoid, participating in metastasis prevention." (PMID 34681197, 2021). "Overexpression of C1GalT1 occurs in various cancer types of epithelial origin." (PMID 34944925, 2021). "Thus, regulation of C1GalT1 overexpression in cancer occurs at least at the transcription level and likely involves multiple regulators." (PMID 34944925, 2021). "Although C1GALT1 expression is only partially suppressed by itraconazole in mouse models, our results open a new avenue to developing small molecules targeting C1GALT1 with higher specificity and affinity for cancer treatment." (PMID 29930379, 2018). "As cell-ECM interaction is the initial step for cancer cell movement and metastasis, we investigated whether C1GALT1 regulates cell adhesion to ECM proteins." (PMID 25089569, 2014). "Furthermore, C1GALT1’s role extends to the epithelial-mesenchymal transition (EMT) in cancer cells." (PMID 38699634, 2024). "C1GalT1 overexpression in epithelial cancers therefore may represent a fundamental mechanism in cancer promotion and in reduction of immune response/surveillance in cancer progression." (PMID 37612278, 2023). "Higher C1GalT1 expression seen in many epithelial cancers therefore may represent a fundamental mechanism in cancer promotion and also in reduction of immune response/surveillance in cancer development and progression." (PMID 37612278, 2023).
cancer (continued). "Results of this study shed light on the novel prognostic role of C1GALT1 in NB, in contrast with adult cancers, and provide new information of C1GALT1 and TrkA on the pathogenesis of NB, which could further help to develop new therapeutic strategies for NB in the future." (PMID 35169131, 2022). "The mechanism of C1GalT1 overexpression in cancer remains largely unknown." (PMID 34944925, 2021). "In conclusion, this study highlights the critical role of C1GALT1‐mediated O‐glycosylation in regulating the surface localization and stability of ABCC1, suggesting potential implications for cancer drug resistance." (PMID 39844613, 2025). "The relationship (Spearman's p correlation and rho values) between C1GALT1 and C1GALT1C1(Cosmc) gene in various cancer types." (PMID 40548474, 2025). "The strong positive correlation observed between C1GALT1 and Cosmc (C1GALT1C1) expression across multiple cancer types reinforces the well‐established functional dependency of T‐synthase on its specific molecular chaperone, Cosmc." (PMID 40548474, 2025). "Furthermore, inhibition of C1GALT1 caused a significant reduction of galectin-3-mediated cell–cell aggregation and cell adhesion to basement proteins, while resulting in an increase of galactose-type lectin (MGL)-mediated heterotypic aggregates formed by macrophages with cancer cells." (PMID 38662050, 2024). "Clearly, C1GalT1 may have different kinetic properties for GalNAc glycosylated O-glycopeptides, but in normal cells, most if not all O-glycans are elongated to mask exposure of the cancer-associated Tn structure." (PMID 35504880, 2022). "In this study, the authors found that overexpression of C1GALT1 regulated glycosylation and phosphorylation on FGFR-2, thereby promoting cancer growth." (PMID 32075174, 2020). "Further investigation indicated that miR-141-3p had a negative correlation with C1GALT1 and suppressed cancer carcinogenesis in TC cells." (PMID 38845937, 2024). "Aberrant glycosylation of MUC1 plays a role in cancer development and progression.The effect of C1GALT1 on MUC1 glycosylation plays a role in CRC development, and cancer therapies targeting MUC1 show potential, suggesting a potential effect of C1GALT1 on MUC1 glycosylation." (PMID 38699634, 2024). "C1GALT1 has a modulatory effect on expression of target glycoproteins such as MUC16, Muc5Ac, and MUC1, and regulates progression of certain types of cancer." (PMID 35864552, 2022). "Since T antigens can be further extended to form more complex O-glycans, it should be noted that the effects of C1GALT1 on MUC1 and cancer cell behaviors could be resulted from core 1 and core 1 derived O-glycans." (PMID 25762620, 2015). "Moreover, C1GALT1 affects downstream signaling pathways and cellular behaviors, such as the epithelial-mesenchymal transition (EMT), by modifying O-glycans on key receptors like FGFR2, enhancing cancer cell invasiveness and metastatic potential." (PMID 38699634, 2024). "Since EGF and bFGF play critical roles in malignant progression and stemness in many cancers and we have found that C1GALT1 can modulate sphere forming ability induced by EGF and bFGF, we therefore analyzed whether these two signaling pathways are involved in the C1GALT1-mediated phenotypic changes." (PMID 24758762, 2014). "Although C1GALT1 is closely related to glycosylation and glucose metabolism, its effect on GLUT1 has not been thoroughly studied in various cancers." (PMID 38845937, 2024).
infection (4 papers, 2011 to 2024). The state of being infected such as from the introduction of a foreign agent such as serum, vaccine, antigenic substance or organism. "Notably, unlike the phenotype caused by SLC39A9 knockout, we found that C1GalT1 knockout in Huh7.5.1-VP30 cells did not impair EBOVΔVP30-EGFP infection, indicating that SLC39A9-mediated glycosylation has limited effect on EBOV infection." (PMID 39173055, 2024). "Further extension of Tn antigen towards glycan core 1 biosynthesis (provided by C1GALT1 activity) was predicted to be upregulated after infection with RVC but not RVA strains." (PMID 37848925, 2023). "For the glycosyltransferases involved in mucin biosynthesis, GCNT3 and GCNT4, both involved in the synthesis of core structures, were found to be up-regulated during infection, while C1GALT1 a key enzyme for the core 1 formation was not affected by the infection." (PMID 21569362, 2011).
C1GALT1 also shares sentences with these, for which no sentence is quoted: cholangiocarcinoma (2 papers); gastritis (2); kidney disease (2); breast invasive carcinoma (1); colorectal cancer 1 (1); COVID-19 (1); esophageal squamous cell carcinoma (1); Ewing sarcoma (1); genitourinary cancers (1); glomerulonephritis (1); intestinal inflammation (1); kidney inflammation (1); Nephropathy (1); prostate tumor (1); serous carcinomas (1); uterine cancer (1); viral infection (1).